PPIAL4G (peptidylprolyl isomerase A like 4G)
Description:
PPIases accelerate the folding of proteins. It catalyzes the cis-trans isomerization of proline imidic peptide bonds in oligopeptides (By similarity).
Synonyms: COAS-2
Tractability: No criterion of Open Targets' tractability assessment is met for any kind of drug.
Gene: Protein-coding gene on chromosome 1 (148,482,548 to 148,483,302, reverse strand). Ensembl gene ENSG00000236334.
Subcellular location: Cytoplasm
Gene Ontology:
Molecular function: cyclosporin A binding; peptidyl-prolyl cis-trans isomerase activity
Biological process: protein folding
Cellular component: cytoplasm
Genetic constraint (gnomAD): Loss-of-function variants: 3 observed, 4.22 expected, observed/expected ratio (o/e) 0.71, 90% interval 0.32 to 1.67. That is too few expected variants to judge how well the gene tolerates losing a copy. Missense variants: 124 observed, 137.44 expected, observed/expected ratio (o/e) 0.9, 90% interval 0.78 to 1.05. Synonymous variants: 41 observed, 52.19 expected, observed/expected ratio (o/e) 0.79, 90% interval 0.61 to 1.02.
Homologues: Orthologues: zebrafish ppifa (68% identical), zebrafish ppiab (68% identical), Caenorhabditis elegans cyn-3 (65% identical), Caenorhabditis elegans cyn-7 (64% identical), zebrafish ppiaa (64% identical), Caenorhabditis elegans cyn-2 (63% identical), Caenorhabditis elegans cyn-1 (60% identical), Caenorhabditis elegans cyn-9 (49% identical), Drosophila melanogaster Cyp40 (48% identical), Drosophila melanogaster Moca-cyp (46% identical). Paralogues in human: PPIAL4C (98% identical), PPIAL4A (96% identical), PPIAL4E (96% identical), PPIAL4F (96% identical), PPIAL4H (96% identical), PPIAL4D (96% identical), PPIA (85% identical), PPIF (66% identical), PPIE (60% identical), PPID (60% identical), PPIB (55% identical), PPIC (52% identical), and 10 more.
Diseases named in the same sentence as PPIAL4G in open-access papers:
PPIAL4G is named in the same sentence as 1 disease in open-access papers, as found by Europe PMC text mining. Sharing a sentence is not in itself a finding about the gene and the disease.
PPIAL4G shares sentences with these, for which no sentence is quoted: melanoma (1 paper).